C9orf43 (chromosome 9 open reading frame 43)
Synonyms: MGC17358
Tractability: PROTAC: ubiquitination databases record sites on it.
Gene: Protein-coding gene on chromosome 9 (113,410,054 to 113,429,690, forward strand). Ensembl gene ENSG00000157653.
Subcellular location (Human Protein Atlas): Cytosol
Gene Ontology:
Molecular function: protein binding
Genetic constraint (gnomAD): Loss-of-function variants: 43 observed, 56.47 expected, observed/expected ratio (o/e) 0.76, 90% interval 0.6 to 0.98. The upper end of that interval is the gene's LOEUF score, 0.98, which puts it in group 4 of 6, group 1 being the genes least tolerant of losing a copy. Missense variants: 487 observed, 547.96 expected, observed/expected ratio (o/e) 0.89, 90% interval 0.82 to 0.96. Synonymous variants: 193 observed, 197.28 expected, observed/expected ratio (o/e) 0.98, 90% interval 0.87 to 1.1.
Homologues: Orthologues: chimpanzee C9H9orf43 (98% identical), macaque C15H9orf43 (90% identical), guinea pig C9orf43 (59% identical), dog C9orf43 (57% identical), rat C5h9orf43 (45% identical), mouse 4933430I17Rik (44% identical).